AGAP2-AS1 (AGAP2 antisense RNA 1)
Synonyms: LOC100130776; PUNISHER
Gene: Long non-coding RNA gene on chromosome 12 (57,726,271 to 57,728,356, forward strand). Ensembl gene ENSG00000255737.
Diseases named in the same sentence as AGAP2-AS1 in open-access papers:
AGAP2-AS1 is named in the same sentence as 9 diseases in open-access papers, as found by Europe PMC text mining. Sharing a sentence is not in itself a finding about the gene and the disease. The quoted sentences say what the papers report.
breast carcinoma (4 papers, 2020 to 2025). "Ultimately, it was proved that encapsulation of AGAP2AS1 into exosomes and its secretion outside breast cancer cells is done in an hnRNPA2B1-dependent manner." (PMID 39925739, 2025). "In trastuzumab-resistant breast cancer cells, hnRNPA2B1 is overexpressed or silenced, and exosome AGAP2AS1 expression is upregulated or downregulated." (PMID 33987099, 2021). "In trastuzumab-resistant breast cancer cells, hnRNPA2B1 is overexpressed or silenced, and exosome AGAP2AS1 expression is correspondingly up-regulated or decreased." (PMID 33987099, 2021). "Recently, lncRNA AGAP2-AS1 (AGAP2 antisense RNA 1) has been reported to play crucial roles in some tumours, such as colorectal cancer, pancreatic cancer, and breast cancer." (PMID 34034689, 2021).
lung carcinoma (2 papers, 2021 to 2025). "We aimed to identify the effect of the lncRNA AGAP2 antisense RNA 1 (AGAP2-AS1)/miR-296/notch homolog protein 2 (NOTCH2) axis on the progression and radioresistance of lung cancer." (PMID 33972506, 2021).
cancer (2 papers, 2021 to 2022). A tumor composed of atypical neoplastic, often pleomorphic cells that invade other tissues. "LncRNA AGAP2 antisense RNA 1 (AGAP2-AS1), transcribed from a gene located at 12q14.1, a novel cancer-related lncRNA, was dysregulated in cancers." (PMID 34899682, 2021).
AGAP2-AS1 also shares sentences with these, for which no sentence is quoted: atherosclerosis (1 paper); colon cancer (1); colorectal cancer (1); non-small cell lung carcinoma (1); pancreatic cancer (1); tumours (1).